TNF (tumor necrosis factor)
Diseases named in the same sentence as TNF in open-access papers (continued):
Sharing a sentence is not in itself a finding about the gene and the disease.
tumor (continued). "Other than immune-modulating cytokines such as IL-10, IL-17, IL-23, and TGF-β (assisting tumor growth), IFN-γ, TNF-α, GM-CSF, IL-2, IL-6, IL-17, and IL-1 stimulate immune surveillance and prevent tum development." (PMID 38951583, 2024). "The majority of TNFα signals in SARIFA-positive and SARIFA-negative tumors were found in the tumor cells (Fig. 6C1a-f)." (PMID 37874427, 2024). "In a tumor spheroid model of human gastric adenocarcinoma cell line HGC27, TNF-α and INF-γ were used as stimulants in order to trigger the production of PD-L1 which in turn allowed to study the mechanistic effects of PD-L1 blockade." (PMID 38254117, 2024). "Main mast cells mediators have been described in the tumor microenvironment, including chymase, tryptase, VEGF, Histamine, TNF-α, MMP2, MMP-9, TIMPs, NGF, and sphingosine-1-phosphate." (PMID 38969910, 2024). "Using human tumour samples and murine subcutaneous tumour models, we demonstrated that TNF-α-induced TNFR2+CCR8+ Tregs were more immunosuppressive and able to dampen antitumour T cell responses, thus promoting tumour growth." (PMID 37935468, 2024). "One peptide, CATH-1, was able to decrease tumor size, which correlated with increased production of TNFα and INF-γ, caspase activation and tumor necrosis." (PMID 38989014, 2024). "Second, they kill tumor cells indirectly by secreting cytokines, such as interferon-γ (IFN-γ), tumor necrosis factor-α (TNF-α) and lymphotoxin." (PMID 38693513, 2024). "When T cells are activated by corresponding tumour antigens, they express surface activation markers such as 41BB, CD69 and CD25 and produce effector molecules such as IL-2, TNF-α, IFN-γ, perforin and granzymes." (PMID 38727812, 2024). "Given that exhausted T cells showed impaired cytokine production, we investigated the expression levels of TNF-α, IFN-γ and IL-2 in tumor-infiltrating T cells." (PMID 38287103, 2024). "Activated CD8+ T cells express homing and chemokine receptors and kill tumor cells by producing high levels of IFN-γ and TNF-α." (PMID 39221244, 2024). "These signals can promote either a pro-tumor M2 phenotype (e.g., IL-4, IL-10, TGF-beta, and CCL2) or can drive TAMs towards an anti-tumor M1 phenotype (e.g., IFN-gamma and TNF-alpha)." (PMID 38730679, 2024). "CXCL1 and CXCL12 promote tumor cell migration, CXCL5 increases angiogenesis while TNF-α affects immune-mediated clearance." (PMID 38175424, 2024). "Among these, IL-1B, IL-6, TNF, CXCLs, TGFB1, HMGB1, STAT3, and STAT5 have been reported to contribute to tumor formation." (PMID 39156107, 2024). "CTLs also enhance tumor cell killing by secreting cytokines like interferon-γ (IFN-γ) and tumor necrosis factor-α (TNF-α)." (PMID 39315102, 2024). "This pattern is completely logical as inhibition of IL-10 allows for less immunosuppression, more angiogenesis, and more VEGF, IL-1β, TNF-α, IL-6, MMP-9, and NF-κB activation, which encourages tumor volume." (PMID 39451257, 2024). "Proinflammatory cytokines such as tumor necrosis factor (TNF)-α and interferon (IFN)-γ induce PD-L1 expression in various cell types, including immune, parenchymal, and tumor cells." (PMID 38799168, 2024). "Firstly, the treatment of tumor cells with inosine enhances the activation of IFN-γ and TNFα signaling pathways." (PMID 38617841, 2024). "Western blot analysis of tumor specimens revealed higher protein expression levels of TNFα, phosphorylated p38 (p‐p38), and MMP9 in the TNFα overexpression group." (PMID 38739004, 2024). "Different mechanisms have been identified as drivers of NET formation, indirectly by the immune cells in the TME, or directly by the tumor cells by releasing various molecules such as IL-1, IL-6, IFN, TNF-α, C3a, HMGB1, or G-CSF." (PMID 39001538, 2024). "TEMs (CD3+CD8+CD44+CD62L−) play an important role in secreting TNF-α and IFN-γ to eliminate tumor cells." (PMID 38807377, 2024).
tumor (continued). "TAMs in CCA are primarily of the M2 phenotype, influenced by the STAT3 pathway, and release cytokines (TNF-α, TGF-β, IL-6, IL-10, VEGF-A) that support tumor growth and metastasis." (PMID 39335203, 2024). "Despite the fact that TRAIL, TNFα and Fas share common pro-apoptotic partners and modalities, only TRAIL displays tumour selective pro-apoptotic activity, sparing normal tissues or cells, including when administered to small animals or humans." (PMID 38534365, 2024). "This combination significantly increased the number of CD8+ tumor‐infiltrating T lymphocytes (TIL) expressing IFN‐γ and TNF‐α and resulted in a higher percentage of circulating CD8+ T cells expressing IFN‐γ and TNF‐α in the draining lymph nodes and the spleen." (PMID 39267574, 2024). "VHH, which binds and neutralizes cytokines or growth factors such as TNFα or VEGF, respectively, can attenuate tumor growth by inhibiting metastasis or angiogenesis." (PMID 38254860, 2024). "As expected, the proportion of matured and activated DC cells in tumor cells of mice treated with SN38-NPs or SN38-URNPs was increased significantly, and this was accompanied by elevated levels of IFN-γ, IL-6, and TNF-α in the serum." (PMID 38571953, 2024). "Decreased TNF-α and IFN-γ expression was observed in adoptively transferred tumor-infiltrating CD8+ T cells in Rag1−/− mice challenged with Id2fl/flCd4-Cre+ CD8+ T cells plus Id2fl/flCd4-Cre− CD4+ T cells." (PMID 38287103, 2024). "AlloIgG combined with the dendritic cell stimuli tumor necrosis factor alpha and CD40L induced tumor eradication via the reported and our proposed potential signaling pathways." (PMID 38461238, 2024). "Tumor necrosis factor-α (TNF-α) is the earliest and most critical inflammatory mediator in the inflammatory response process, possessing cytotoxic effects on tumor cells." (PMID 39061859, 2024). "This process is facilitated by the production of various cytokines and chemokines, including TNF-α, IFN-γ, IL-2, IL-12, IL-21, IL-15, IL-18, CXCR3, and granulocyte-macrophage colony-stimulating factor (GM-CSF), which actively promote anti-tumor immunity." (PMID 38533507, 2024). "TCRs expressed by Vδ2 T cells preferentially couple with the Vδ2 and Vγ9 chains and directly target tumor cells via perforin and granzyme or indirectly target these cells through the release of IFN-γ and TNF-α." (PMID 38515134, 2024). "Upon surgical resection, the cancer cells undergo trauma, and such tumor cells can enhance the generation of cytokines and other factors, including IL-6, C-reactive protein (CRP), TNF-α, IL-1β to affect the immune system." (PMID 38566199, 2024). "KLK6 is a secreted serine protease, which promotes the production of TNF-α by macrophages through PAR1 in the TME to stimulate the production of CXCL1 in tumor cells, thereby promoting tumor growth and metastasis." (PMID 38363409, 2024). "The result suggested that dMMR tumor cells were more sensitive than pMMR tumor cells to PANoptosis with co-treatment of IFN-γ and TNF-α." (PMID 38740747, 2024). "Of note, the delay of tumor growth induced by low-dose G4-TNF was similar to that induced by low doses (50 and 100 pg) of murine CNGRCG-TNF (called NGR-TNF), while a comparable dose (50 pg) of TNF was totally inactive." (PMID 38289472, 2024). "Once infused in vivo, CAR-NK cells recognize tumor cells efficiently and kill tumor cells by releasing substances like IFN-γ and TNF-α and directly inhibiting tumor cell proliferation or inducing apoptosis." (PMID 39664387, 2024). "The secretion of serum killer cytokines TNF-α and IFN-γ in tumour-bearing nude mice in the experimental group treated with EpCAM-CAR-T cells was higher than that in the blank and control groups (P < 0.05)." (PMID 39107717, 2024). "TGF-β upregulates the expression of Claudin 4 and its translocation to the nucleus to activate the NF-κB/TNFα signaling pathway to induce mesenchymal transformation of GBM cells and enhance cell invasion and tumor growth." (PMID 38256140, 2024).
tumor (continued). "Along these lines, restimulation of CK-exposed CD8+ cells yielded reduced induction of IFNγ and TNFα, two signature effector cytokines of cytotoxic CD8+ cells involved in tumor clearance." (PMID 38570506, 2024). "The MSLN CAR‐iNK cells exhibit a robust increase in the expression of IFN‐γ, TNF‐α, and CD107a upon stimulation by MSLN‐expressing tumour cells." (PMID 39136096, 2024). "CTLs are known for their strong anti-tumor capabilities, while Th cells support CTLs and B cells and can directly target tumor cells by releasing IFN-γ and TNF-α." (PMID 39199375, 2024). "The 16-biomarker panels were divided into three categories of inflammatory markers (SAA, CRP, NLR, PLR, and LDH), TH1/TH2 cytokines (IL-2, IL-4, IL-5, IL-6, IL-8, IL-10, IFNγ, TNF, and GM-CSF), and HCC tumor markers (AFP and PIVKA-II)." (PMID 38409200, 2024). "In contrast, TAMs were found to emit a considerable quantity of growth factors and cytokines, including vascular endothelial growth factor (VEGF) and tumor necrosis factor-alpha (TNF-α), to promote tumor angiogenesis and assist invasive tumor growth." (PMID 38653742, 2024). "Tumor proliferation pathways like TGF and TNF were directed to the low MC region, while the tumor suppressor stimulator of interferon genes (STING) pathway flowed to the high MC region, implicating potential tumor recurrence." (PMID 39015573, 2024). "In both the CD8 TIL-tumor coculture and the CD8 CEA-CAR coculture, increased levels of TNF were observed, as well as increased IL-6 and AREG levels in the anti-CEA-CAR system." (PMID 38226976, 2024). "Under the influence of tumor antigens encoded by BNT111, activated CD4+ T cells differentiate into Th1, Tfh and Treg cells, enhancing tumor eradication by secreting cytokines like IFN-γ and TNF." (PMID 39460333, 2024). "TAMs themselves are recruited to premetastatic niches by a variety of tumor-secreted factors, such as CCL2, CSF-1, VEGF, PDGF, TNF-α, and TGF-β, where they act in a similar manner as in primary tumors, promoting cancer cell survival." (PMID 39516356, 2024). "Inflammatory cytokines, such as interleukin-6 (IL-6) and tumor necrosis factor-alpha (TNF-α), are elevated during COVID-19 infection and can create an environment conducive to tumor growth and metastasis." (PMID 39156288, 2024). "They promote the proliferation and differentiation of CD8+ T cells and regulate TNF-α and IFN-γ secretion, enhancing tumor clearance rates." (PMID 38933280, 2024). "Ex vivo neutrophil-activating therapy consisting of TNF, anti-CD40, and tumor-binding antibody allows rapid recruitment of neutrophils to tumors." (PMID 39769334, 2024). "In contrast, the activity of tumor-infiltrating CD4+ and CD8+ T cells was significantly enhanced by cisplatin, as evaluated by their ability to secrete cytokines, e.g., INF-γ and TNF-α." (PMID 39343834, 2024). "B16 mouse melanoma tumor cells and DU145 prostate cancer cells, showed high STAT3 activity by increasing phosphorylation of RelA protein in the presence of TNF-α." (PMID 38571491, 2024). "Some inflammatory mediators or cytokines, such as interleukin-6 (IL-6) and tumor necrosis factor-alpha (TNF-α), can promote tumor growth and metastasis." (PMID 38731833, 2024). "TMPyP4 therapy significantly increased the percentages of IFNγ+, TNFα+, and Perforin+ CD8+ T cells in the tumor microenvironment compared to control groups." (PMID 39528472, 2024). "Tumors formed by CT26 KO2 + Mlh1 induced partial expression of perforin, granzyme B, and TNF-α and partial activation of N-GSDMD and N-GSDME, which also inhibited tumor growth in CT26 KO2 + Mlh1, with little difference in tumor volume compared to CT26 KO." (PMID 38740747, 2024). "The results showed that XLLXF combined with trastuzumab significantly increased the levels of IL-15, IL-2, TNF-α, and IFN-γ in the sera of tumor-bearing nude mice." (PMID 38379418, 2024). "pMMR tumor cells had defects in the PANoptosis pathway and were resistant to co-treatment of IFN-γ and TNF-α." (PMID 38740747, 2024).
tumor (continued). "With regard to literature, TNF-α is often employed in tumor biotherapy, whereas IFN-γ has been shown to mitigate tumor cell proliferation." (PMID 38882349, 2024). "Identified targets reflect tumor cell sensitivity or resistance under T cell pressure, typically affecting antigen presentation, IFN and TNF signaling, and cytotoxic T cell killing functions." (PMID 39538305, 2024). "M1 macrophages exert antitumor effects primarily through the secretion of cytokines, including interleukin-6, interleukin-12, and tumor necrosis factor α (TNF-α), which directly kill tumor cells." (PMID 39676861, 2024). "TNF/STAT3 pathway participates in the regulation of diverse biological processes and ultimately plays a crucial role in tumour formation, metastasis, and drug resistance." (PMID 39586790, 2024). "The majority of CD4(+) T cells expressed either TNF-α and/or IFN-γ, indicating a T-helper 1 (Th1) subset predominance in the tumor infiltrates." (PMID 38895115, 2024). "Neutrophil-derived TNF regulates immunologic rewiring, CXCL1 overproduction from tumor cells, and T cell dysfunction." (PMID 38474175, 2024). "MHY1485 suppresses tumor growth in vivo under co-treatment with X-rays and increases INF-γ, tumor necrosis factor, interleukin-2 and interleukin-12 levels in the spleen as well as the presence of CD8+ cells in the tumor." (PMID 38330507, 2024). "Both in vitro and in vivo experiments and the use of VGX-1027, an inhibitor of macrophage-derived TNF-α and IL-1β, confirmed that SPP1 + Mac-derived TNF-α and IL-1β promoted HNSCC progression by supporting tumor cell proliferation and migration." (PMID 39726047, 2024). "Cytokines like tumor necrosis factor alpha (TNF-α), TGF-β, IL-6, IL-10 and IL-17 secreted in either an autocrine, endocrine or paracrine manner have assumed a pivotal role in promoting tumor survival and metastasis." (PMID 38254117, 2024). "To further understand the pro-inflammatory impact of GzB-IL18, we co-cultured pCAR-H/T T cells and their armored derivatives with MDA-MB-468 tumor cells or anti-CD3+CD28 beads and measured tumor necrosis factor (TNF)-⍺ and IL2 in derived supernatants." (PMID 38745414, 2024). "Apart from chemokines, the anti-tumor capacity of CD8+T cells was largely regulated by pro-inflammatory cytokines such as IL-6 and TNF-α." (PMID 38291473, 2024). "highlight that in TNBC, Vδ2+ T cells are the predominant γδTILs subgroup, actively contributing to anti-tumor effects by secreting IFN-γ and TNF-α." (PMID 38933280, 2024). "Tumor necrosis factor alpha (TNF-α) is involved in many tumor cell pathological cellular pathways, including tumor invasion, epithelial-mesenchymal transition, vascular invasion, and the destruction of tumor vasculature." (PMID 39252946, 2024). "For example, neutrophils from men produce a greater amount of tumor-necrosis factor (TNF) than women; hormones also affect immune cells, where they impact anti-tumor immunity and treatment response." (PMID 38647024, 2024). "The co-cultivation of CAR-T cells with CAR-DCs to target Kasumi-1 tumor cells demonstrated increased cytotoxicity (78.4% CAR-DC+CAR-T vs. 39.9% CAR-T vs. 17.6% eGFP T cells) and production of IFN-γ, TNF-α and IL-12 compared to CAR-T alone or the eGFP-control." (PMID 39061247, 2024). "These gut-educated ex-Th17 cells produce high levels of the pro-inflammatory cytokines IFN-γ and TNF-α, and promote expansion and effector functions of CD8+ tumor-infiltrating cytotoxic lymphocytes, thereby controlling tumor growth." (PMID 39185202, 2024). "On the other hand, Th17 cells inhibit tumor angiogenesis by secreting TNF-α, IFN-γ, IL-17F, IL-21 and IL-22, which inhibit tumor growth and promote the apoptosis of cancer cells." (PMID 39534095, 2024). "The pro-inflammatory cytokines (TNF-α, IFN-γ, and IL-6) in both mouse plasma and tumor tissues showed a significant increase after treatment with PAC-SABIs, while a notable decrease was observed in the anti-inflammatory cytokine TGF-β." (PMID 38971872, 2024).
tumor (continued). "Serum HMGB1, which increased in tumor-bearing rats, was reduced to one-tenth with BBR treatment, while TNFα reduced by one-third." (PMID 38731953, 2024). "Markers of tumor burden and inflammation (LDH, CRP, IL-6, IL-10, TNF-α, ferritin, fibrinogen, D-dimer) were correlated with aph-PET and car-PET features." (PMID 38649972, 2024). "TNF-α increases the invasiveness of PDAC cells and promotes tumor growth and metastasis development." (PMID 39273323, 2024). "Th1 subtype of CD4+T cells directly destroy tumor cells by secreting IFN-γ and TNF, whereas Th2 subtype secretes anti-inflammatory mediators such as IL4, which suppress immunity and support tumor growth." (PMID 39350256, 2024). "The same anti-PD1 treatment in mouse models of CD8 + T cells’ depletion or TNF-guided neutralization induced an increase in the incidence of NASH-related HCC and tumor nodules (number and size)." (PMID 38732000, 2024). "The supplement using SCFAs increases intra-tumor T cells, raising the concentration of cytokines INF-γ and TNF-α." (PMID 39229258, 2024). "Human blood conventional dendritic cells (cDCs) acquire the ability to kill tumor cells via TRAIL, FasL expression, or TNF-α, perforin, and granzyme secretion." (PMID 38903193, 2024). "The results showed that TNF-α and IL-1β activated the NF-κB signaling pathway and then promoted OPN expression in tumor cells and tumor cell progression." (PMID 39726047, 2024). "M-CSF induces regulatory macrophages for homeostasis, and GM-CSF generates inflammatory macrophages, secreting IL-6, IL-1β, and TNF-α, with IFN-γ enhancing this production, potentially aiding tumor growth." (PMID 38713256, 2024). "The findings indicate that pomalidomide exhibits the ability to enhance proliferation of T cell, sustain the anti-tumor effect of CAR-T cells, and stimulate the release of cytokines IFN-γ and tumor necrosis factor (TNF)-α." (PMID 38433987, 2024). "SerpinB3 expression increases in response to Tumor Necrosis Factor (TNF)-α and Ras-driven inflammation leading to NF-kB activation, IL-6 production and tumor growth." (PMID 39061218, 2024). "For instance, DC-sEVs expressed TNF, FasL, and TRAIL on their surfaces, enabling them to induce cancer cell apoptosis through caspase signaling in tumor cells." (PMID 38476233, 2024). "Tumour cell death was accompanied by the release of IFN-β, TNF-α, and IL-6 (attributed to cGAS/STING activation in the surrounding immune milieu following immunogenic cell death), all of which are drivers of anti-tumour inflammation." (PMID 39403376, 2024). "Albeit IFNγ was decreased in tumor supernatants, intracellular staining in CD3+ cells revealed slightly increased IFNγ and TNFα signals after oxTAA injection." (PMID 38958560, 2024). "Tumor necrosis factor (TNF) combats tumors through multiple mechanisms including tumor cell apoptosis, disrupting tumor vasculature, and activating immune cells." (PMID 39669560, 2024). "The gene expression profile revealed upregulation of several certified immune-activated gene clusters, including TNF-α and IFN-γ, in tumor immunity effect cells following MSA administration." (PMID 38550593, 2024). "TAMs secrete cytokines such as TNF-α, TGF-β, and IL6, which regulate the CCA microenvironment and promote epithelial-mesenchymal transition, tumor growth, and metastasis." (PMID 39660136, 2024). "This was accompanied by a decrease in the induction and proportion of tumor-infiltrating multifunctional CD8+ T cells expressing IFN-γ, TNF-α, or IL-2." (PMID 38886748, 2024). "Our findings reveal a significant increase in the levels of TNF-α, IFN-γ, and IL-6 in tumor tissue following treatment with AgNPs-G." (PMID 39126001, 2024). "CTLs mediate direct cytotoxic effects on tumor cells upon the releasing of granzyme and perforin, as well as secretion of IFN-γ and TNF-α." (PMID 38514186, 2024).